ZNF552 (zinc finger protein 552)
Description:
May be involved in transcriptional regulation.
Synonyms: FLJ21603
Tractability: PROTAC: UniProt records ubiquitination sites on it; ubiquitination databases record sites on it.
Gene: Protein-coding gene on chromosome 19 (57,803,841 to 57,814,913, reverse strand). Ensembl gene ENSG00000178935.
Subcellular location: Nucleus
Subcellular location (Human Protein Atlas): Nucleoplasm
Pathways (Reactome):
Gene expression (Transcription): Generic Transcription Pathway
Gene Ontology:
Molecular function: protein binding; DNA-binding transcription factor activity, RNA polymerase II-specific; RNA polymerase II cis-regulatory region sequence-specific DNA binding; sequence-specific DNA binding
Biological process: regulation of transcription by RNA polymerase II; regulation of DNA-templated transcription
Cellular component: nucleus
Genetic constraint (gnomAD): Loss-of-function variants: 3 observed, 7.8 expected, observed/expected ratio (o/e) 0.38, 90% interval 0.17 to 0.99. That is too few expected variants to judge how well the gene tolerates losing a copy. Missense variants: 421 observed, 507.41 expected, observed/expected ratio (o/e) 0.83, 90% interval 0.76 to 0.9. Synonymous variants: 173 observed, 179.23 expected, observed/expected ratio (o/e) 0.97, 90% interval 0.85 to 1.1.
Homologues: Orthologues: chimpanzee ZNF552 (90% identical), macaque ZNF552 (89% identical), tropical clawed frog zfx (16% identical), mouse Zfy1 (15% identical), mouse Zfy2 (14% identical), rat Zfy1 (14% identical), zebrafish zfx (14% identical). Paralogues in human: ZNF587B (88% identical), ZNF418 (69% identical), ZNF256 (51% identical), ZNF304 (48% identical), ZNF551 (46% identical), ZNF792 (45% identical), ZNF549 (43% identical), ZNF548 (43% identical), ZIK1 (40% identical), ZNF772 (40% identical), ZNF586 (39% identical), ZNF419 (32% identical), and 26 more.
Diseases named in the same sentence as ZNF552 in open-access papers:
ZNF552 is named in the same sentence as 3 diseases in open-access papers, as found by Europe PMC text mining. Sharing a sentence is not in itself a finding about the gene and the disease. The quoted sentences say what the papers report.
breast carcinoma (1 paper, 2021). "In addition, ZNF552 has been suggested as a regulator of genetic risk of breast cancer and its regulons have shown to be enriched in genes associated with risk loci identified using a combination of GWAS and eQTL analysis." (PMID 33558504, 2021).
cancer (1 paper, 2017). A tumor composed of atypical neoplastic, often pleomorphic cells that invade other tissues. "Others that have been indirectly linked to cancer include HIST1H2AD, two zinc finger proteins (ZCCHC3, ZNF552), and CSRP2, CREBL2, and SERTAD3." (PMID 29282095, 2017).
tumor (1 paper, 2021). "Compared to normal samples, the expression of E2F2, FOXJ1, EMX1, PAX7, NKX6-1, FOXD1, and ZNF552 was significantly higher (P < 0.05) and the expression of MSX1, STAT4, NR3C2, and EGR3 was significantly lower in tumor samples (all P < 0.05)." (PMID 33688372, 2021).